LAG3 (lymphocyte activating 3)
Diseases named in the same sentence as LAG3 in open-access papers (continued):
Sharing a sentence is not in itself a finding about the gene and the disease.
tumor (continued). "New IC molecules, including VISTA, TIM-3, LAG-3, TIGIT, programmed cell death ligand 2 (PD-L2), B7H3, BTLA and GITR, have been identified as potential targets for overcoming tumour heterogeneity and resistance, offering potential for more effective cancer immunotherapy." (PMID 40994140, 2025). "Tumor-infiltrating CD4+ T28zT2 T cells are enriched with TCF-1+IL7R+ memory-like T cells, express NKG2D, and downregulate T cell exhaustion markers, including PD-1 and LAG3." (PMID 40107245, 2025). "LAG-3 overexpression is often correlated with the expression of other inhibitory receptors, such as PD-1 and TIM-3, leading to profound functional exhaustion of T lymphocytes and impairing their ability to eliminate tumor cells." (PMID 40574024, 2025). "Unlike monoclonal antibodies (MAbs), aptamers targeting LAG-3 can be chemically engineered for more potent tumor penetration and prolonged action." (PMID 40870970, 2025). "Additionally, these TCR T cells had reduced expression of the exhaustion markers LAG-3 and TIM-3 following tumour antigen stimulation." (PMID 39859271, 2025). "Furthermore, chronic tumor antigen exposure induces T cell exhaustion, characterized by elevated expression of inhibitory receptors (for example, TIM-3 and LAG-3), which further diminishes ICIs effectiveness." (PMID 40973957, 2025). "Responders to ICIs demonstrated significantly higher proportions of LAG-3+ cells compared with non-responders (p = 0.0210), and patients with ≥1% LAG-3+ tumor cells had significantly longer PFS than those with <1% LAG-3 (p = 0.0037)." (PMID 40981345, 2025). "Tumor cells upregulate PD-L1 expression via genomic amplification, PTEN loss leading to PI3K pathway activation, or interferon signaling induction; other checkpoints like LAG-3, TIM-3, TIGIT are often co-expressed on exhausted T cells, synergistically inhibiting anti-tumor immunity." (PMID 41567982, 2025). "There is a clear correlation between higher expression of LAG3 in TIL and closer proximity of T cells to tumor cells, where LAG3 predicts more CD4 + or CD8 + T cells clustered around the tumor, and immune activation within the TME prompts more effector T cells to exert tumor-killing effects." (PMID 40411616, 2025). "Moreover, it has been shown that the combination of anti-LAG3 and anti-PD1 monoclonal antibodies enhances IFNγ production and T cell cytotoxicity, leading to more effective tumor growth inhibition." (PMID 41019045, 2025). "The overall efficacy of EMB-02 was modest, with an ORR and DCR of 6.4% and 44.7%, respectively, however generally comparable with other anti-PD-1 and anti-LAG-3 bispecific antibodies in dose escalation studies which did not for selected tumor type." (PMID 40234667, 2025). "LAG-3 interacts with major histocompatibility complex class II (MHC-II) molecules to suppress T-cell proliferation, cytokine secretion, and cytotoxic function, thereby weakening anti-tumor immune responses." (PMID 40918452, 2025). "Preclinical studies demonstrate that TIGIT, LAG-3, and CTLA-4 contribute to T-cell exhaustion through distinct mechanisms, and their co-blockade enhances CD8+ T-cell responses, reduces Treg-mediated immunosuppression, and delays tumor growth in murine models." (PMID 40567374, 2025). "Notably, LAG-3 is frequently co-expressed with PD-1 on CD4+ and CD8+ tumor-infiltrating T cells, and their combined blockade has shown enhanced immunotherapeutic efficacy." (PMID 40723175, 2025). "In addition, this molecule showed a positive correlation with the expression of PD-1, CTLA-4, TIGIT, LAG-3, and TIM-3, indicating its involvement in the immune exhaustion process in the tumor microenvironment." (PMID 40965626, 2025). "Also, in the anti-tumor immune process, there are some other immune checkpoints, including CTLA-4, TIM3, LAG3, NKG2A, and so on, which are also recognized and participate in co-regulating immune responses with anti-PD-L1 therapy." (PMID 39900923, 2025).
tumor (continued). "T cells in the tumor of mice and humans exhibited high expression of CD39 and CD73, two ectoenzymes involved in the production of immunosuppressive adenosine from ATP, along with increased expression of PD-1, LAG-3 and GITR." (PMID 39751916, 2025). "LAG-3 KO anti-CD19 CAR T cells also demonstrated a significantly decreased tumor size compared to CAR T cells with no gene KO." (PMID 41354926, 2025). "Our analysis revealed that CD4 + and CD8 + T cells in closer proximity to the tumor core during treatment exhibited greater activation, potentially accompanied by negative feedback upregulation of LAG3 expression." (PMID 40411616, 2025). "Ongoing trials are evaluating whether adding a second checkpoint inhibitor (such as an anti-CTLA-4 antibody) to PD-1 blockade plus chemotherapy can deepen responses, or if novel checkpoints (LAG-3, TIGIT, etc.)might further augment anti-tumor immunity in BTC." (PMID 41007662, 2025). "Strategies under investigation include combination therapies with other immune modulators (e.g., LAG-3, TIGIT inhibitors), targeted therapies (e.g., EGFR or KRAS inhibitors), and epigenetic modulators that reprogram the tumor microenvironment to be more immunogenic." (PMID 41584608, 2025). "The tumor-preventive effects primarily involved the suppression of regulatory T cells and a low level of T cell exhaustion in the periphery (PD1+), as well as in the spleen, identified by reduced numbers of LAG-3+ splenocytes in both treatment groups." (PMID 40674934, 2025). "Evaluation of exhaustion markers in TILs following tumor-cell rechallenge revealed a slight decrease in the frequency of LAG3+ cells, but no changes in PD1+ or CD39+ expression were observed in ABE-TILs." (PMID 41394272, 2025). "Similarly, significantly elevated percentages of CD8+ T cells expressing LAG-3 (31.50 ± 8.33% of CD8+ T cells), and PD-1 (13.01 ± 3.82% of CD8+ T cells) were detected in tumor tissues, as well." (PMID 41221283, 2025). "Blocking TIM-3, LAG-3, and TIGIT can synergize with PD-1 blockade to restore the proliferative capacity of exhausted CD8+ T cells in tumors and upregulate NK cell activation, thereby enhancing tumor-killing effects." (PMID 40821806, 2025). "Furthermore, preclinical models demonstrate that early inhibition of LAG3 significantly enhances prognosis in GBM-bearing mice and is highly effective in tumor eradication when combined with anti-PD-1/PD-L1 therapy." (PMID 40376586, 2025). "This suggests that TIM-3 and LAG-3 can mark clonally expanded, tumor-reactive T cells in inflamed tumors rather than exclusively indicating terminal exhaustion." (PMID 40943541, 2025). "In most cancer types, PTEN loss was associated with a higher abundance of CD4+ lymphocytes, M1 macrophages, and FoxP3+ T regulatory cells, along with increased expression of immune checkpoints such as LAG3 and IDO1, indicating an immunosuppressive tumor microenvironment." (PMID 40650023, 2025). "Studies have shown that human CD8 + T cells often express KIRs and NKG2 A in a mutually exclusive manner, and the absence of PD-1 and LAG3 allows NKG2 A to impede the anti-tumor immunity of CD8 + T cells." (PMID 40411616, 2025). "Msh2loxP/loxP; TgTg(Vil1-cre mice without clinical signs of tumor development (i.e. age <12 weeks) received repeated applications (n = 8, 28-day interval) of anti-PD-L1, anti-LAG-3 (2.5 mg/kg bw, i.p.)or isotype (anti-IgG1, 2.5 mg/kg bw, i.p.)." (PMID 40674934, 2025). "Additional in vitro co-culture experiments with tumor cells and peripheral immune cells, either with or without immune-checkpoint blockade with anti-PD-L1, anti-LAG-3, or a combination of both confirmed the therapeutic activity of these antibodies." (PMID 40674934, 2025). "In tumor-bearing models, obese mice show more aggressive tumor growth and a TME enriched in dysfunctional CD8+ tumor-infiltrating lymphocytes expressing high levels of PD-1, Tim3, and Lag3." (PMID 41432903, 2025).
tumor (continued). "Furthermore, the upregulation of alternative immune checkpoints, such as LAG-3, TIGIT, B and T lymphocyte attenuator (BTLA), and TIM-3, can further suppress the immune response and enable tumor progression despite ongoing ICI therapy." (PMID 40087690, 2025). "In addition, the proportions of ICOS+, LAG3+, 4-1BB+, and OX40+ tumor-infiltrating iNKT cells were higher compared with circulating iNKT cells from patients or HDs." (PMID 41562072, 2025). "Notably, tumor-infiltrating CD8+ T cells from SATB1-CAR-T group exhibited 50% lower PD-1, CTLA-4, TIM3, and LAG-3 expression compared to controls, aligning with their exhaustion-resistant phenotype in vitro." (PMID 41372119, 2025). "Tumor cells exploit molecules like PD-1, CTLA-4, and LAG-3 to suppress cytotoxic immune responses." (PMID 41244711, 2025). "Prior studies have shown a high percentage of T cells in tumor-infiltrating lymphocytes (TILs) in ESCC tumors, and LAG-3 expression may be high on CD8 + TIL from ESCC, playing an important role in regulating CD8 TIL function alongside PD-1." (PMID 40234667, 2025). "Moreover, PD-L1/LAG-3 BsAbs, such as IBI323, achieve 75% inhibition, accompanied by an increase in tumor-infiltrating lymphocytes (TILs)." (PMID 41239350, 2025). "Studies indicate that combining γδT cells with chemotherapy, immune checkpoint inhibitors (such as anti-LAG3, PD1, or PDL1 antibodies), radiotherapy, or interventional therapy can effectively mitigate TME-induced immunosuppression, thereby enhancing anti-tumor activity." (PMID 40141420, 2025). "Tumor CD8+ T cells were also most enriched with CD103+CD69+ resident memory T cells (Trm; 24.6% in tumor vs. 8.4% in MPE vs. 0.3% in blood) and exhibited the highest expression of the co-inhibitory receptors PD-1, LAG-3, TIGIT, and TIM-3." (PMID 41415427, 2025). "In addition, SCC tumours exhibited a higher frequency of CD4+ and CD8+ T cells co-expressing TIM-3 with PD-1, and also LAG-3 co-expressed more often with other checkpoint molecules on CD8+ T cells, suggesting a more exhausted immune state in SCC than in AC." (PMID 40639721, 2025). "Similarly, dual immune checkpoint blockade, such as targeting PD-1 in combination with CTLA-4, LAG-3, TIM-3, or TIGIT, has shown potential in restoring anti-tumor immunity, particularly in refractory settings." (PMID 40723175, 2025). "The galectin-3 produced by tumor cells and macrophages blocks CD8+ T cell activation signals and induces T cell apoptosis by interacting with LAG3 on the T cell surface; while FOXP3+ Tregs suppress anti-tumor immunity by secreting various inhibitory cytokines, such as TGF-β, IL-10 and IFN-γ." (PMID 41219968, 2025). "Tumor sections were stained with checkpoint markers: PD1, CTLA4, LAG3, TIGIT, and TIM3." (PMID 40067762, 2025). "CX-5461 modestly inhibited tumour growth and significantly sensitized tumours to anti-Lag3 immunotherapy, but had no adverse effects on body weight." (PMID 40646287, 2025). "Similarly, murine studies of selinexor showed reduced LAG-3, T-cell immunoglobulin and mucin-domain containing-3 (TIM-3) and PD-1 expression on tumour-infiltrating CD8+ T cells." (PMID 40291981, 2025). "Notably, depletion of GPATCH3 led to significant upregulation of CXCL8, CCL5, LAG3, and PVRL2 —genes with well-established roles in immune cell recruitment, immune checkpoint signaling, and tumor–immune interactions." (PMID 40861452, 2025). "PD-1 and LAG-3 double knockout CD8+ T cells exhibit higher TCR diversity, stronger cytotoxicity (increased expression of GZMB and PRF1), and IFN-γ dependent anti-tumor effects, while the combination of PD-1 with TIM-3 or TIGIT blockade is still in the exploratory stage." (PMID 40821806, 2025). "First, the majority of tumor samples were obtained via biopsy rather than surgical resection, which restricts our ability to fully evaluate intratumoral heterogeneity in LAG-3 expression and its impact on prognosis and treatment outcomes." (PMID 39751894, 2025).
tumor (continued). "Notably, several of these checkpoints (e.g., PDCD1, LAG3, TIGIT and CTLA4) collectively impair T cell function through distinct mechanisms, driving immune evasion and tumor progression." (PMID 41562077, 2025). "Furthermore, PRAME silencing reduced the frequency of CD8+ T cells expressing the immune checkpoints PD-1, LAG-3, and VISTA, indicating that PRAME tumor expression significantly impairs the PD-L1/PD-1 axis by dysregulating both the ligand and its receptor." (PMID 40141328, 2025). "In addition, the combination of LAG-3, PD-1, and Tim-3 enhances B-granzyme production by CD8+ tumor-infiltrating lymphocytes (TILs) and increases the cytotoxic activity of T lymphocytes against cancer cells." (PMID 40361336, 2025). "Additionally, CD8+CD161+ T-cells demonstrated lower expression of exhaustion markers, LAG-3 (p = 3E-7), TIM-3 (p = 0.05), and PD-1 (p = 3E-7), pointing towards a more robust and sustained anti-tumor response." (PMID 40165951, 2025). "Consequently, during radiotherapy, the ligands of NPC tumor cells bind to inhibitory receptors on NK cells, including TIM-3, LAG3, and TIGIT, thereby reducing NK cell cytotoxicity." (PMID 40936698, 2025). "Over time, tumor escape mechanisms, such as the upregulation of other immune checkpoints (e.g., TIM-3, LAG-3), the persistence of regulatory T-cells, or the re-establishment of an immunosuppressive tumor microenvironment, may enable tumor growth." (PMID 41011180, 2025). "TIGIT may be co-expressed in tumor cells alongside other receptors, including PD-1, TIM-3, and LAG-3." (PMID 40574024, 2025). "Furthermore, we observed increased tumor uptake of 99mTc‐HYNIC‐αLAG‐3 probe and LAG‐3 expression on IHC in LLC‐bearing LAG‐3 humanized mice with primary resistance to immunotherapy." (PMID 39513410, 2025). "Interestingly, LAG-3 was predominantly co-expressed with TIM-3 on CD8+ TILs and was highly expressed on CD4+ T cells in both ascites and tumor tissues." (PMID 41315319, 2025). "However, as receptor occupancy was determined using an in vitro assay in isolated donor cells overexpressing LAG-3, a higher dose of INCAGN02385 (350 mg Q2W) was selected to account for potentially lower drug availability within the tumor." (PMID 40631774, 2025). "Interestingly, melanoma patients treated with anti-PD-1 (nivolumab) and anti-LAG-3 (relatlimab) in the RELATIVITY-047 clinical trial showed enhanced NKG2A expression on circulating, tumour-specific CD8+ T cells compared to pre-treatment." (PMID 40291981, 2025). "A similar trend was also observed in the HepG2 tumor-bearing model: The tumor volume in the PBS group was 941.46 mm3, that in the Jurkat cell group was 765.83 mm3, and that in the LAG3-apt + Jurkat group and the HER2-apt + Jurkat group decreased to 433.16 mm3 and 400.60 mm3, respectively." (PMID 40761795, 2025). "Responses to ICB have been associated with TIICs, an increase in tumor-infiltrating PD-1hiCD8+T cells, LAG3+CD8+T cells and monocytes/macrophages in tumor as well as S100A9+CD14+monocytes in the peripheral blood of patients exhibiting suboptimal responses to anti-PD-1 therapy." (PMID 41438767, 2025). "In addition, although our investigation revealed treatment-induced modulation of the CPS, LAG3, and β-catenin, we did not detect statistically significant associations between either pre- or post-treatment values of these markers and patient survival or tumor recurrence." (PMID 40483270, 2025). "Therefore, even though there was an increase in TIM-3 and LAG-3 on CAR T cells after their engagement with PDA cells, we preferred to manipulate the ICs from the PDA tumor side, in another word, on PD-L1 molecule." (PMID 40861475, 2025). "While the proportion of CD4+CD25highCD127low regulatory T cells (Treg) was numerically highest in MPE (6.9% in MPE vs. 3.8% in tumor vs. 4.2% in blood), MPE Tregs possessed lower levels of activation markers (CD69, HLA-DR) and co-inhibitory receptor (PD-1, LAG-3, TIM-3) expression." (PMID 41415427, 2025).
tumor (continued). "There was concurrent and significantly increased expression of the immune checkpoint pathway markers HAVCR2 (TIM-3), CTLA-4, PDCD1 (PD-1), PDCD1LG2 (PD-L1), LAG3, and TIGIT, demonstrating increased immune suppressive signaling from both the tumor and immune cell populations." (PMID 38418892, 2025). "Therefore, in the present study, we investigated ESCC patients with different activation profiles of LAG3 and TIL and analyzed their prognostic value in tumor therapy." (PMID 40411616, 2025). "Promising preclinical results using combination strategies, including dual checkpoint blockade targeting LAG-3 and TIM-3 alongside PD-1 inhibition, as well as epigenetic modulation with histone deacetylase inhibitors, offer hope for enhancing anti-tumor immunity." (PMID 41268982, 2025). "The CellphoneDB analysis of ligand-receptor pairs showed that the interaction networks between UPP1high tumor cells and FOXP3+ Tregs/LAG3 + PDCD1 + CD8 + T cells were involved with numerous immune checkpoints, including CD274/PDCD1LG2_PDCD1, FGL1_LAG3, and NECTIN_TIGIT." (PMID 38331898, 2024). "T cells lacking LAG-3 can bypass Treg suppression and differentiate into Th1 cells, thereby enhancing anti-tumor responses." (PMID 39743998, 2024). "In the CLL mouse model, dual anti-PD-1/LAG-3 therapy reduced the percentage and number of CLL cells in both the blood and spleen, thus effectively reducing the tumor burden in CLL-infected animals, which represented an effective treatment for restoring a functional antitumor immune response." (PMID 38581716, 2024). "The phenomenon of “exhaustion” is the consequence of a chronic stimulation of T cells by tumor cells that lead to the upregulation of immune checkpoint markers such as PD-1, LAG-3 and TIGIT on T cells, rendering TILs inadequate at exerting an effective anti-tumor immune response." (PMID 39594814, 2024). "Together, our data suggest that NF1, TSC1, or TβRII inactivation resulted in a tumor cell non-autonomous immune suppressive microenvironment that is potentially mediated by LAG3+ CD8 T and CD4 T cells." (PMID 38997291, 2024). "The investigators further found that receptors for the immune checkpoint molecules PD‐1, LAG‐3, and TIM‐3 were more common in tumors containing TLS and with high tumor‐infiltrating lymphocyte (TIL) density, which might explain its prognostic significance." (PMID 38469550, 2024). "Additionally, another one cluster in tumor region the was characterized by lymphocytes and immune inhibitory markers (including CD4, CD8, NK, NKT, B cells, memory T, LAG3, TIM3, CTLA4, IDO and PD-1)." (PMID 38373959, 2024). "Fibrinogen-like protein 1, an immunosuppressive ligand of LAG-3, was also not detectable in tumor cell culture supernatants." (PMID 39075115, 2024). "LAG-3 expression in CD8 T cells is activated through binding its ligands on cancer cells, resulting in the CD8 T cells being inactivated, exhausted, and therefore unable to kill the tumor cells, inducing cancer immune evasion." (PMID 39796650, 2024). "In addition, tumor sections collected on day 10 post-treatment were stained for immune cells (CD45+) and LAG-3." (PMID 38349406, 2024). "Immunoassay shows DLD’s high expression may reduce T cell-mediated anti-tumor immunity by regulating CD276 and immune checkpoints LAG3 positively and regulating CD8 + T cells’ immune infiltration." (PMID 38581529, 2024). "As LAG-3 expression increased on TILs including CD8+ TPEX in the tumors after anti-metabolite chemotherapy, we sought to determine if adding anti-(a)LAG-3 with anti-(a)PD-1 ICB would improve anti-tumor immunity after chemotherapy." (PMID 39343508, 2024). "The blockade of PD-1 and/or LAG-3 has been demonstrated to enhance the anti-tumour efficacy of vaccines in three non-glioma tumour models." (PMID 38660136, 2024). "LAG-3 and MHC class II binding contributes to the recruitment of tumor-specific CD4+ T cells." (PMID 39796650, 2024).